CCND1 (cyclin D1)
Diseases named in the same sentence as CCND1 in open-access papers (continued):
Sharing a sentence is not in itself a finding about the gene and the disease.
glioma (continued). "A recent study reported that both cyclin E and cyclin D1 may have a key role in promoting the growth of glioma cells, as well as their transformation into malignant cells." (PMID 26043756, 2015). "Furthermore, ectopic expression of Cyclin D1 statistically counteracted the G1 arrest induced by miR-15b in glioma cells." (PMID 24995320, 2014). "In addition, Pearson's correlation coefficient showed a significant inverse correlation between miR-15b and Cyclin D1 in glioma tissues (R = −0.79125 P < 0.01)." (PMID 24995320, 2014). "Moreover, expression of miR-15b in glioma tissues was found to be inversely correlated with Cyclin D1 expression." (PMID 24995320, 2014). "Our findings identified that miR-15b may function as a glioma suppressor by targeting the Cyclin D1, which may provide a novel therapeutic strategy for treatment of glioma." (PMID 24995320, 2014). "Moreover, recent studies demonstrated that a number of cell cycle-related and invasion-associated genes are regulated by IGF-1R, including CCND1 and MMP-2/MMP-9 in human glioma and head and neck cancer, which function through MAPK and PI3K/AKT pathways." (PMID 24378652, 2014). "Moreover, we show that miR-195 inhibited glioma cell proliferation by downregulating expression of cyclin D1 and cyclin E1, via directly targeting the 3′-untranslated regions (3′-UTR) of cyclin D1 and cyclin E1 mRNA." (PMID 23383003, 2013). "Finally, very low pHe (6.0) arrested glioma cells in the G1 phase of the cell cycle as a downstream result of cyclin D1 mislocalization and degradation in T98G human glioma cells." (PMID 24198789, 2013). "As cell cycle arrest is a prerequisite of differentiation, it is reasonable to relate the role of TCE in regulating cell cycle and leading to G0/G1 and G2/M cell cycle arrest with down-regulation of cyclin D1 and consequently differentiation of the C6 glioma cells." (PMID 24205314, 2013). "Glioma cells co-cultured with hUCBSC showsreduced expression of cyclin D1 in both cell lines." (PMID 21455311, 2011). "Moreover, overexpression of CDKN2A inhibits growth of glioma cell lines by suppression of cyclin D1 gene expression." (PMID 21843312, 2011). "Importantly, it should be noted that several works have demonstrated that the levels of cyclin D1 are increased in human glioma biopsies that could well be a consequence of the reduction of α-syn protein levels." (PMID 40108111, 2025). "LINC00887 may also drive the malignant progression of glioma via upregulating Cyclin D1 (CCND1)." (PMID 38338866, 2024). "Moreover, the Western blotting results showed that HYAL2 knockdown decreased the relative levels of the cell cycle-associated proteins CCNB1 and CCND1 in glioma cells, further suggesting that silencing HYAL2 could induce cell cycle arrest in glioma." (PMID 37568202, 2023). "Furthermore, KDELR2 can regulate cellular function in glioma cells by targeting CCND1." (PMID 36474171, 2022). "Therefore, we examined the expression of CCND1 in glioma samples." (PMID 34758200, 2021). "Therefore, this study hypothesized that there might be an E2F1/miR‐107/CCND1 axis involved in the pathogenesis of glioma." (PMID 34758200, 2021). "Additionally, we could detect an inhibitory effect on cyclin D1 expression, confirming previous data, suggesting it as a downstream target of oncogenic MAPK-signaling in BRAF-mutated glioma." (PMID 31391125, 2019). "We conclude that even if there is a heterogeneous nitric oxide production by the xenografted glioma cells that impacts Vegfa and Cyclin D1 expression levels, our results suggest that reduction of nitric oxide levels by nitric oxide scavenging could be an efficient approach to treat glioma." (PMID 25768009, 2015). "Importantly, co-expression of Cyclin D1 and Cyclin E1 indeed could further potentiate the proliferation of glioma cells, compared to that of Cyclin D1 or Cyclin E1 expressed alone." (PMID 23383003, 2013).
glioma (continued). "Quercetin significantly reduces T98G and U87 glioma cell proliferation and migration by inhibiting STAT3 phosphorylation, primarily through the downregulation of two STAT3 target genes: cyclin D1 and MMP-2." (PMID 40733274, 2025). "A related study found that hepatogenic growth factor acts in conjunction with c-Jun to induce CCND1/CDK4/CDK6 expression and promote the proliferation of gliomas." (PMID 40138292, 2025). "Cyclin D1 (CCND1) and Cyclin D2 (CCND2) are key regulators of cell proliferation in various cell types, including glioma cells, placental trophoblast cells, and granulosa cells." (PMID 41460875, 2025). "In glioma and ovarian cancers, NAP1L1, via its interaction with HDGF, activated c-Jun, an oncogenic transcription factor, to induce CCND1/CDK4/CDK6 expression resulting in cellular proliferation and chemoresistance to cisplatin." (PMID 40176914, 2025). "In U251 glioma cells, STMN1 knockdown inhibited both cyclin D1 and cyclin B expression while upregulating p21 expression, leading to cell cycle arrest in vitro." (PMID 40723207, 2025). "Its predicted target genes include four hub genes, CCND1, SP1, CDK6 and CDK4, which are directly or indirectly involved in glioma development." (PMID 39348350, 2024). "Western blotting was used to show that the expression of Wnt/β‐catenin pathway‐related proteins, including β‐catenin, c‐Myc, cyclin D1, CD44 and Met, was remarkably decreased in NSC‐CM‐treated glioma cells." (PMID 37410396, 2023). "The upregulation of NAP1L1 increased its binding with c-Myc and, further, activated c-Myc, which induced the expression of CCND1/CDK4 and thereby promoted the resistance to temozolomide and proliferation of glioma cells." (PMID 37770914, 2023). "Naringenin supplementation for 1 month can reduce lipid peroxidation and decrease the expression of PKC, NF-κB, cyclin D1(CCND1) and cyclin-dependent kinase 4 (CDK4), thereby inhibiting the proliferation of glioma cells in mouse models." (PMID 38130720, 2023). "Upregulation of NAP1L1 increased its binding with c-Myc and activated c-Myc, which induced the expression of CCND1/CDK4, promoting glioma cell temozolomide resistance and proliferation." (PMID 37770914, 2023). "The upregulation of NAP1L1 increased its binding with c-Myc and thereby activated c-Myc, inducing the expression of CCND1/CDK4 and thereby promoting glioma cell temozolomide resistance and proliferation." (PMID 37770914, 2023). "Overexpression of TIPE2 prevents hypoxia-induced expression of β-catenin, cyclin D1, and c-myc in human glioma cells, suggesting that TIPE2 overexpression inhibits hypoxia-induced activation of the Wnt/β-catenin pathway and EMT in glioma cells." (PMID 35054779, 2022). "In the brain of orthotopic glioma mice, the expression of downstream targets of PI3K/AKT signaling that regulate GBC proliferation and apoptosis resistance, e.g., Cyclin D1 and Bcl-2, was significantly increased compared with that in tumor-free brains." (PMID 36147923, 2022). "We found that the protein levels of cyclin D1, CDK6 and CDC6 were reduced in UM-164-treated glioma cells in both dose- and time-dependent manners." (PMID 36358761, 2022). "The overexpression of β-catenin in high-grade gliomas is a possible outcome of the aberrant activation of the canonical Wnt/β-catenin pathway, which in turn leads to the activation of CCND1 and MYC in gliomas." (PMID 36358663, 2022).
glioma (continued). "we performed the co-expression analysis and confirmed that CAPG2 positively correlates with the expressions of well-defined glioma stem cell marker genes, including Sox2, CD44, MYC and CCND1." (PMID 35898895, 2022). "Reduced cyclin D1 levels, selective downregulation of Akt Ser473 phosphorylation, and VEGF receptor levels in parkin‐expressing glioma cells promote G phase cell cycle arrest and slow down the proliferation rate of glioma cells." (PMID 37786890, 2022). "In the current study, P-β-catenin, Cyclin D1, β-catenin, and C-myc levels expressed in the Wnt pathway were positively regulated by USP25 in U251 and U87 glioma cells." (PMID 35450028, 2022). "Upregulated miRNA-363 increased glioma cell viability and proliferation by adjusting the expression level of GAP-43, AKT,cyclin-D1 and other factors." (PMID 34338136, 2021). "The expression levels of Wnt-related genes, including β-catenin, GSK-3β, cyclin D1, and CD44 were all decreased in AEG-1 knockdown glioma cells compared to that in the control cells." (PMID 34462446, 2021). "For example, in vivo and in vitro experiments have shown that c-myc, CCND1, Bcl-2, BCL-XL, Survivin, etc., are the direct target genes of STAT3 in the regulation of glioma cell proliferation." (PMID 34425834, 2021). "Western blot analysis and IHC showed that cyclin D1, cyclin D2, CDK4, CDK6, Ki-67, Bcl-2 and Bax were involved in the NRXN3-induced inhibitory effect on glioma growth." (PMID 34035217, 2021). "Cyclin D1 and CDK4 are downstream proteins of AKT which control cell cycle regulation and promote glioma cells proliferation." (PMID 34485271, 2021). "In glioma, PKM2 mediates phosphorylation of histone H3 on threonine 11, resulting in the transcriptional activation of c-MYC, cyclin D1 and tumour progression." (PMID 34847775, 2021). "For example, Alqudah MA elucidated that via activation of CCND1 and EGFR, NOTCH3 promotes glioma cell proliferation, migration and invasion." (PMID 33676540, 2021). "Cyclin D1 and CDK4 are key proteins in the regulation of the cell cycle and are overexpressed in human gliomas." (PMID 34485271, 2021). "Then, Western blot analysis was performed to investigate the effect of curcumin on cyclin D1, CDK4/6, Bcl‐2 and Bcl‐XL in glioma cells." (PMID 34169637, 2021). "miR-23a overexpression promoted the proliferation and inhibited the apoptosis of glioma cells, as well as increased AKT and PI3K phosphorylation and Cyclin D1 protein levels." (PMID 33085646, 2020). "Cell proliferation and cell division were very closely related, and the only study on gliomas showed that ARG blocked the cycle in a concentration-dependent manner, and blocked the cycle in G 0/G1, and reduced cyclin D1 protein levels." (PMID 33015162, 2020). "It has also been reported that miR-638 targets HOXA9 3’UTR directly, downregulates HOXA9 expression, and thus inhibits the two Wnt signaling effectors c-Myc and Cyclin D1, while overexpression of HOXA9 can partially abolish the miR-638 effects in glioma." (PMID 33154193, 2020). "In fact, BCP treatment significantly down-regulated Cyclin D1 and its cyclin-dependent kinase (CDK) 4 in both U373 glioblastoma cell line and in glioma stem cells." (PMID 32340197, 2020). "While determining the mechanisms that miR‐5188 promotes glioma progression, we confirmed that overexpression of miR‐5188 up‐regulated protein levels of CDK4, CCND1, c‐JUN, N‐cadherin and vimentin." (PMID 32902145, 2020). "Silencing OIP5-AS1 reduced cell proliferation, invasion and migration of glioma U87 cells and led to depressed expression levels of miR-410, Wnt-7b, p-β-catenin, GSK-3β-pS9, c-Myc and cyclin D1." (PMID 30498093, 2019).
glioma (continued). "We also revealed a novel mechanism of glioma malignance driven by GATAD1 by sequentially inducing histone acetylation, chromatin conformation interaction and transcription of CCND1 gene." (PMID 31286678, 2019). "Coherent exposition to SRT2183 provoked a prominent decrease in G1 phase-related protein such as Cyclin D1 and pRb in LN229 and U87MG cell lines, accompanied by a decrease in ki67 staining in SRT2183-treated glioma cells." (PMID 31319814, 2019). "Expression of proliferation marker proteins, including cyclin D1 and proliferating cell nuclear antigen (PCNA), was significantly downregulated as well in circPRKCI-silenced A172 glioma cells." (PMID 31409777, 2019). "PIWIL1 also regulates apoptosis and cell cycle progression through P21, Cyclin D1, BCL-2 and BAX, and migration through expression of MMP-2 and MMP-9 in glioma cells." (PMID 31443431, 2019). "The expression levels of global SUMOylation, SAE1, AKT, p-Akt, Cyclin D1, CDK2, p21, Bcl-2 and active Caspase-3 were increased in the SAE1-overexpressing glioma tissues." (PMID 31345225, 2019). "Then, these reduced phosphorylation levels of β-catenin led to increases in its endogenous level and downstream regulator expressions such as cyclin D1, suggesting that IGF-1 activated the WNT/β-catenin pathway in glioma U87-MG cells." (PMID 31805126, 2019). "The anti-tumor activity of miR-149 in glioma cells was found to be correlated with low-expression of PCNA, p-AKT1, cyclin D1, and MMP-2." (PMID 31297133, 2019). "Consistently, IHC staing of CCNB1, CCND1, and CDK4 of the 21 glioma specimens confirmed that the protein expression levels of these cell cycle gene are correlated with PRMT2 in different grades of gliomas." (PMID 30382083, 2018). "To further explore the pathway through which miR-29a/b/c suppress glioma cell proliferation, we focused on the crucial effectors downstream of TRAF4, including AKT, GSK-3β, c-Myc, and the G1/S-phase checkpoint regulator cyclin D1." (PMID 30348972, 2018). "We show that miR-449 directly targets and downregulates CCND1, resulting in reduced proliferation in vitro, and GPR158, antagonising neural differentiation and apoptosis in glioma stem cells." (PMID 29720725, 2018). "In the Glioma pathways (KEGG), 3 genes were down-regulated by both citalopram and escitalopram (E2F1, DAPK1, CCND1)." (PMID 28467792, 2017). "However, the potential correlation between the CCND1 G870A polymorphism and glioma risk is not clear yet, till now, limited population based studies have been conducted to investigate the association between CCND1 G870A polymorphism and glioma risk." (PMID 28380465, 2017). "Expression of Ki67, MMP-9, Cyclin D1, Bcl-2 and C-myc was varied in accordance with the level of TAZ in glioma cell." (PMID 27764783, 2016). "Positive feedback of cyclin D1 activation (e.g., through cyclin D1 auto-activation or the cyclin D1/CDK4-6/Rb/E2F/cyclin D1 feedback loop) has been demonstrated to be involved in glioma differentiation." (PMID 27515956, 2016). "The apparent Hill coefficients of the simulated dose-response curves for cyclin D1 and GFAP with respect to CT were 40 and 43, respectively, indicating strong ultrasensitivity in the response of glioma differentiation to drug treatment." (PMID 27515956, 2016). "Consistently, the transcriptional and translational levels of Cyclin D1 and p27kip1, two downstream effectors of PI3K/Akt signaling, were also significantly alliterated in the miR-93-deregulated glioma cells." (PMID 25823655, 2015). "In glioma cells, overexpression of cyclin D1 increased matrix metalloproteinase (MMP) activity and cellular motility, which are responsible for malignant progression of glioma." (PMID 25971210, 2015). "In this investigation, we examined key cell growth regulators and observed that Cyclin D1, Cyclin E1, pRb, and NF-κB were downregulated after stable ENO1 knockdown in glioma U251 and U87 cells." (PMID 24650096, 2014).
glioma (continued). "Treatment of glioma U251 and U87 cells with LY294002 had a similar effect on E-Cadherin, Cyclin D1, and p-Rb as ENO1 knockdown." (PMID 24650096, 2014). "In the present study, it was found that Notch2 signaling in U87 human glioma cells increased the proportion of cells in the S phase and upregulated MCM2 and cyclin D1 protein expression levels; however, p21 protein expression was downregulated." (PMID 25323114, 2014). "Mechanistic analyses revealed that Cyclin D1, Cyclin E1, pRb, and NF-κB were downregulated after stable ENO1 knockdown in glioma U251 and U87 cells." (PMID 24650096, 2014). "Furthermoe, the levels of several NF-κB target genes, TNF-α, IL-6, CCND1, MYC, BcL-XL and MMP-9, were upregulated in Bmi-1-overexpressing, but downregulated in Bmi-1-silenced glioma cells." (PMID 23383216, 2013). "As predicted, upregulation of miR-195 decreased, but inhibition of miR-195 increased, the expression levels of cyclin D1 and cyclin E1 in LN18 and T98G glioma cells." (PMID 23383003, 2013). "Furthermore, we also examined whether the Akt inhibitor can synergize with miR-329 in inhibiting proliferation in glioma cells, the levels of Akt phosphorylation are decreased by treatment with Akt inhibitor IV, in which the p21 is significantly increased and cyclin D1 is decreased." (PMID 23866847, 2013). "However, the addition of the cell cycle activator Cyclin D1 partially restored the inhibitory effect of TUBA1B knockdown on cell migration and invasion, further validating that TUBA1B regulates glioma cell behavior through the cell cycle." (PMID 40094001, 2025). "The results of western blotting showed that the expression of Wnt/β‐catenin signalling pathway‐related proteins, including β‐catenin, c‐Myc, cyclin D1, CD44 and Met, was significantly lower in glioma cells treated with NSC‐CM than in those treated with the control medium." (PMID 37410396, 2023). "Accordingly, in a previous study, we have described an increment in Cyclin D1 expression in pediatric gliomas where IGF1R had nuclear compared to non-nuclear localization." (PMID 35574033, 2022). "GPR158 can regulate the malignant phenotype of glioma, and, as a biomarker, quantitatively characterize the malignant process of glioma independent from the miR-449a target CCND1 (the expression of CCND1 remains largely independent of the tumor subtype)." (PMID 35456013, 2022). "The results demonstrated that the expression of c-Myc, cyclin D1, cyclin A, and E2F1 decreased after knocking down TFE3, suggesting that the TFE3-mediated overexpression of HOXD-AS2 promoted the cell cycle progression in glioma cells." (PMID 35269968, 2022). "In contrast, there is no specific enrichment with a FOXM1 antibody at the promoters of H19, myoglobin and CCND1 3 which are genes non-expressed or imprinted in glioma cells (they serve as negative controls)." (PMID 34131149, 2021). "Functional experiments have shown that overexpression of miR-506 could inhibit the migration and invasion of glioma cells and reduce the protein expression levels of MMP2, cyclin D1 and Bcl-2." (PMID 34425834, 2021). "The results showed that CCND1, CDC42, RAF1, and CHEK1 were highly expressed in gliomas." (PMID 33676540, 2021). "JHU-083 reduced glioma cell growth in vitro, modulated cell metabolism, and disrupted mTOR signaling and downregulated Cyclin D1 protein expression, through a mechanism independent of TSC2 modulation and glutaminolysis." (PMID 33681764, 2021). "To sum up, we unearthed that M2 macrophage-derived miR-15a and miR-92a could target CCND1 and RAP1B, respectively, thereby inhibiting the invasion and migration via blocking PI3k/AKT/mTOR signaling pathway in gliomas." (PMID 33676540, 2021). "In summary, NAP1L1 could promote proliferation and chemoresistance in glioma cells by interacting with HDGF and activating c-Jun to induce the expressions of CCND1/CDK4/CDK6." (PMID 34959221, 2021).